CDK4 (cyclin dependent kinase 4)
Diseases named in the same sentence as CDK4 in open-access papers (continued):
Sharing a sentence is not in itself a finding about the gene and the disease.
breast cancer (continued). "Although mutations in the kinase domain of CDK4 and CDK6 have not been reported as mechanisms of resistance to CDK4/6i, CDK6 amplification was described in CDK4/6i-resistant breast cancer cell models." (PMID 34771560, 2021). "Our study suggests that acquired resistance to PAL or ABE confers cross-resistance to the other CDK4/6 inhibitor but not to chemotherapeutic agents in HR-positive, HER2-negative breast cancer cells." (PMID 32860163, 2021). "Our ChIP assay showed that the ER did not interact with the CDK2 or CDK4 promoter region, suggesting that BC-N102 downregulated the expression of CDK2 and CDK4 independent of ER positivity in breast cancer cell lines." (PMID 34421361, 2021). "Due to low toxicity but high and long-lasting response rates of CDK4/6 inhibition, these drugs should be used in all patients with hormonal receptor positive and HER2 negative advanced breast cancer until more reliable biomarkers become available." (PMID 32934773, 2020). "Overall, we inferred that breast cancer with low p21 expression largely depends on the CDK2–cyclin E complex to progress to the S-phase; thus, CDK4 and CDK6–cyclin D complex are no longer necessary to overcome the G1–S checkpoint." (PMID 31448056, 2019). "Palbociclib, a cyclin-dependent kinases 4 and 6 (CDK4/6) inhibitor is approved for metastatic estrogen receptor (ER)-positive and human epithermal growth factor 2 (HER2)-negative breast cancer." (PMID 29261702, 2017). "Interestingly enough, the activity of CDK4 has been found not to strictly follow cyclin D1 expression in breast cancer cell lines, a finding suggesting that CDK4-independent functions of cyclin D1 may contribute to its biological effects as an oncogene in breast cancer." (PMID 28797035, 2017). "Palbociclib, an inhibitor of CDK4 and CDK6, in combination with endocrine therapy resulted in improved progression-free survival (PFS) in ERα+/Her2 negative advanced breast cancer." (PMID 29228549, 2017). "This induction and expression of pS294 in wt ER-positive or ERmut-positive breast cancers can be prevented by CDK2 inhibitors, but not by CDK4/6 inhibitors." (PMID 29137354, 2017). "In particular, CDK4 expression significantly correlated with ER and PR negative, but not HER2 status of breast cancers." (PMID 27759034, 2016). "Functional Rb protein is required for CDK4/6 to regulate the G1 restriction point; the mechanism of action for LY2835219 was further defined in breast cancer cell lines with and without functional Rb." (PMID 24919854, 2014). "While cyclin D1/CDK4 specifically mediates centrosome amplification triggered by H-RasG12D, H-RasG12D&c-Myc, and in HER2+ breast cancer cells, silencing of cyclin E or CDK2 have no impact on centrosome amplification in the HER2/Ras systems." (PMID 23886499, 2013). "A recent study is consistent with our results, as chemical inhibition of CDK4 and CDK6 in breast cancer cells did not influence double-strand break repair after irradiation." (PMID 23886499, 2013). "We present data showing that knockdown of CDK4, but not of CDK2, imparts radiosensitivity to breast cancer cells and normal mammary epithelial cells by signaling an apoptotic program." (PMID 23886499, 2013). "Although CDK4 and CDK2 are promising targets in cancer therapeutics, their role in the response of ER-PR-HER2+ or ER-PR-HER2- breast cancer cells to ionizing radiation is controversial and not extensively explored." (PMID 23886499, 2013). "Cyclin-dependent kinase 4 and 6 (CDK4/6) inhibitors are currently in widespread use for the treatment of both advanced metastatic and early-stage hormone receptor (HR)-positive, human epidermal growth factor receptor (HER2)- negative breast cancer." (PMID 42037944, 2026).
breast cancer (continued). "At present, combining CDK4/6 inhibitors (such as palbociclib, ribociclib, or abemaciclib) with endocrine therapy represents the leading treatment strategy for individuals with hormone receptor positive and HER2 negative advanced breast cancer." (PMID 41148817, 2025). "In terms of clinical data, the CDK4/6 inhibitor palbociclib did not appear to significantly affect estradiol and FSH levels in patients affected by breast cancer, while no data are available with the two approved CDK4/6 inhibitors, abemaciclib and ribociclib, in the adjuvant setting." (PMID 40482082, 2025). "Recent years, cyclin-dependent kinase 4 and 6 inhibitors (CDK4/6i), including palbociclib and ribociclib, have been used for the treatment of hormone receptor-positive (HR+), human epidermal growth factor receptor-negative (HER2-) advanced breast cancer (ABC)." (PMID 40746611, 2025). "Current NCCN and Japanese Breast Cancer Society (JBCS) guidelines in this subgroup do not include clear and standardized recommendations on the optimal treatment sequence or subsequent treatment options after CDK4/6 inhibitor therapy." (PMID 41156245, 2025). "Ribociclib and palbociclib, CDK4/6 inhibitors available in Turkey, have become the first-line option in HR(+)/HER2(-) advanced breast cancer patients without visceral crisis when combined with aromatase inhibitors or endocrine therapy (ET), and their use has rapidly increased." (PMID 40142360, 2025). "This review offers an expert perspective on biomarkers, CDK4/6 inhibitor efficacy, and therapeutic approaches for managing hormone receptor-positive (HR+), human epidermal growth factor receptor-negative (HER2-) advanced breast cancer (ABC), particularly after CDK4/6 inhibitor progression." (PMID 39935426, 2025). "Cyclin-dependent kinase 4/6 (CDK4/6) inhibitors are the first-line treatment for hormone receptor-positive (HR+), human epidermal growth factor receptor 2-negative (HER2-) advanced breast cancer in the absence of visceral crisis." (PMID 39114308, 2024). "Despite significant progress with CDK4/6 inhibitors, no phase 3 studies have evaluated the efficacy and safety of palbociclib in combination with tamoxifen in patients with HR+/HER2− advanced breast cancer regardless of menopausal status." (PMID 39174547, 2024). "CDK4/6 inhibitors (CDK4/6i) combined with endocrine therapy are considered standard-of-care for first-line therapy of patients with hormone receptor positive, HER2 negative, advanced breast cancer (HR+/HER2− ABC)." (PMID 36876172, 2023). "Cyclin-dependent kinases 4 and 6 (CDK4/6) inhibitors are a recent targeted therapy approved for patients with hormone receptor-positive (HR+), human epidermal growth factor receptor 2 negative (HER2−) advanced breast cancer." (PMID 37895811, 2023). "Recently, three CDK4/6i (palbociclib, abemaciclib, and ribociclib) have received FDA approval to treat estrogen receptor (ER)-positive, Erb-B2 Receptor Tyrosine Kinase 2 (HER2)-negative advanced breast cancer in combination with endocrine therapy." (PMID 37452037, 2023). "Cyclin-dependent kinase 4 and 6 inhibitors (CDK4/6i) have been increasingly used in the setting of advanced hormone receptor (HR) positive, human epidermal growth factor receptor 2 (HER2) negative breast cancer, as well as in early disease." (PMID 36765648, 2023). "Palbociclib (Ibrance, Pal) is a selective inhibitor of cyclin-dependent kinase 4/6 (CDK4/6) approved by the Food and Drug Administration (FDA) in 2015 for the treatment of hormone receptor-positive (HR+)/HER2 negative (HER2−) breast cancer in combination with hormone therapies." (PMID 37752122, 2023).
breast cancer (continued). "In order to target both upstream ER and downstream CDK4/6 signaling for cancer control, the combination of CDK inhibitors with endocrine therapy has been used successfully in metastatic ER+ breast cancer, and to a moderate extent in earlier-stage, non-metastatic breast cancer." (PMID 37386030, 2023). "Endocrine therapy (ET) with cyclin-dependent kinase 4/6 inhibitor (CDK4/6i) is currently the standard first-line treatment for most patients with hormone receptor (HR) positive, human epidermal growth factor receptor (HER2) negative advanced breast cancer." (PMID 37684290, 2023). "CDK4/6 inhibitors have become the mainstay of treatment for patients with advanced hormone receptor positive and Human Epidermal Receptor -2 [ HER-2 ] negative breast cancer." (PMID 36200010, 2022). "CDK4/6 inhibitors have been approved for treatment of hormone receptor positive (HR+) and human epidermal growth factor receptor 2 (HER2) negative (HER2-) breast cancer in combination with anti-hormonal therapy." (PMID 36067171, 2022). "The extended study of two additional cohorts of the NA-PHER2 trial showed in cohort B of HER2-amplified breast carcinomas that block of HER2 and cdk4/6 led to a rapid and major drop of Ki67 even without the use of estrogen receptor targeting in spite of estrogen receptor expression." (PMID 35013314, 2022). "CDK4/6 inhibitors (CDK4/6i) plus endocrine therapy are the mainstay of treatment for patients with estrogen receptor (ER)-positive, human epidermal growth factor receptor 2 (HER2)-negative advanced breast cancer (ABC)." (PMID 33761970, 2021). "Abemaciclib is a selective cyclin-dependent kinase 4/6 (CDK4/6) inhibitor used in the management of hormone receptor positive (HR +), human epidermal growth factor receptor 2 negative (HER2-) unresectable or recurrent breast cancer." (PMID 33453015, 2021). "Since MRS could compete with p16INK4a for binding to CDK4, the stabilizing effect of MRS on CDK4 was more significant in p16INK4a-negative breast cancer cells." (PMID 33330488, 2020). "Treatment with the p110α-selective PI3K inhibitor, alpelisib (BYL719), completely blocked the progression of acquired CDK4/6 inhibitor-resistant xenografts in the absence of continued CDK4/6 inhibitor treatment in models of both PIK3CA mutant and wild-type ER+/HER2− breast cancer." (PMID 32795346, 2020). "Ribociclib (LEE011) is a highly selective, orally bioavailable CDK4/6 inhibitor that has recently been approved for the treatment of HR-positive, human epidermal growth factor receptor 2 (HER2)–negative advanced breast cancer in combination with an aromatase inhibitor." (PMID 30443290, 2018). "Similarly, targeting CDK1, but not CDK4/6 or CDK2, is selectively lethal to MYC-dependent human breast cancer cells." (PMID 25914884, 2015). "We found that targeting CDK1 rather than CDK4/6 or CDK2 selectively reduced the viability of MYC- dependent breast cancer cells, suggesting a potential therapeutic value of targeting CDK1 for MYC-driven human breast cancer." (PMID 24444383, 2014). "Background and Objectives: Cyclin-dependent kinase 4/6 inhibitors (CDK4/6i) combined with endocrine therapy are recommended as first- or second-line treatment for hormone receptor (HR)-positive, human epidermal growth factor receptor 2 (HER2)-negative advanced or recurrent breast cancer." (PMID 42075533, 2026). "The combination of CDK4/6i with endocrine therapy has significantly improved progression-free survival (PFS) and overall survival (OS) in patients with hormone receptor (HR)-positive, human epidermal growth factor receptor 2 (HER2)-negative advanced breast cancer." (PMID 40430137, 2025). "In recent years, cyclin-dependent kinase 4 and 6 inhibitors (CDK4/6i), including palbociclib, ribociclib, and abemaciclib, have been approved for the treatment of hormone receptor-positive (HR+), human epidermal growth factor receptor-negative (HER2-) advanced breast cancer (ABC)." (PMID 39935426, 2025).
breast cancer (continued). "In two luminal breast cancer lines (T47D and ZR751) with DNM1L knockdown, we found that variations in the residual DNM1L protein among replicates correlated positively with the abundance of CDK4 but not a housekeeping control, as predicted by the positive LASSO dependency." (PMID 39333715, 2024). "In recent years, the combination of targeted drugs, such as Cyclin-dependent kinase 4/6 (CDK4/6) inhibitors, with endocrine therapy (ET), has emerged as a new research focus in the treatment of hormone receptor-positive (HR+) human epidermal growth factor receptor 2 negative (HER2-) breast cancer." (PMID 38832268, 2024). "Endocrine treatment in combination with cyclin-dependent kinase 4/6 inhibitors (CDK4/6i) is the standard of care in first-line and second-line treatment of advanced hormone-receptor positive human epidermal growth factor receptor 2 (HER-2) negative advanced breast cancer." (PMID 38912058, 2024). "Within the group of kinase inhibitors, cyclin-dependent kinase 4/6 (CDK4/6) inhibitors, including Palbociclib and Abemaciclib, have been successfully used in the treatment of advanced estrogen receptor-positive (ER+) and human epidermal growth factor receptor 2 (HER-2)-negative breast cancers." (PMID 37298236, 2023). "The recent addition of cyclin-dependent kinase 4 (CDK4) and CDK6 inhibitors to endocrine therapy has remarkably improved the outcome of patients affected with hormone receptor positive (HR+), human epidermal grow factor receptor 2 negative (HER2 -) advanced breast cancer (ABC)." (PMID 35223478, 2022). "Endocrine therapy, with or without the use of a cyclin-dependent kinase 4 and 6 (CDK4/6) inhibitor, is the current standard of care for patients with advanced hormone receptor-positive (HR+), human epidermal growth factor receptor 2-negative (HER2–) breast cancer." (PMID 35406370, 2022). "In cancer cells, HER2 and CDK4/6 signaling pathways could be nonredundant; co-inhibition of both pathways by combination of SHR6390 and pyrotinib may have synergistic anticancer activity on HER2+/HR+ breast cancer." (PMID 34977029, 2021). "The combination of mTOR or PI3K inhibitors to CDK4/6 inhibitor therapy have shown encouraging preliminary results in clinical trials, although PI3K inhibitors resulted to be quite toxic and poorly effective and, therefore, they are not yet approved for breast cancer." (PMID 32351542, 2020). "In recent years, drugs that inhibit CDK4/6 activity (palbociclib, ribociclib, or abemaciclib) in combination with endocrine therapy have been used to treat patients with ER-positive/human epidermal growth factor receptor 2 (HER2)-negative advanced breast cancer." (PMID 32650578, 2020). "Combining cyclin-dependent kinases 4 and 6 (CDK4/6) inhibitors with endocrine therapy is an effective strategy to improve progression-free survival in hormone receptor-positive (HR+), human epidermal growth factor receptor 2 (HER2)-negative advanced breast cancer." (PMID 30458732, 2018). "Background/Objectives: CDK4/6 inhibitors have changed the landscape of hormone receptor (HR)-positive, human epidermal growth factor receptor 2 (HER2)-negative metastatic breast cancer (BC) management." (PMID 40002286, 2025). "While the direct interactions between CD200 and CDK4/6 pathways are not well documented, the preclinical evidence suggests that the immune modulation from anti-CD200 might potentiate the effects of CDK4/6 inhibitors in hormone receptor-positive, HER2-negative breast cancers." (PMID 39795972, 2024). "Interestingly, tumor types that express other forms of CYCLIN D-CDK4/6 complexes, such as breast cancers in which CDK4 is often in complex with CYCLIN D1, do not undergo apoptosis or exhibit changes in the phosphorylation status of metabolic enzynes in response to CDK4 inhibition." (PMID 36051751, 2022).
melanoma (509 papers, 1996 to 2026). A malignant, usually aggressive tumor composed of atypical, neoplastic melanocytes. "RAF inhibitor and CDK4/6 inhibitor showed a synergistically inhibition for NRAS mutation melanoma in vitro and in vivo." (PMID 41492362, 2026). "Loss of p16 reflects deregulation of the CDK4/6–RB checkpoint and provides a biological rationale for exploring CDK4/6 inhibitors in molecularly selected melanoma subsets." (PMID 41596618, 2026). "Given that the dysregulation of the key mitogenic pathways that regulate Cyclin D is a hallmark of melanoma, we would expect therapies targeting CDK4/6 to have greater clinical efficacy than has been observed." (PMID 40282469, 2025). "In melanoma, mutations and dysregulation are commonly seen in CDK4 and proteins in its pathways, and several candidate drugs are in clinical trials." (PMID 40075679, 2025). "Previously, heterozygous germline mutations in CDK4 (R24C or R24H) causing gain of function were described in familial melanoma cases." (PMID 40210435, 2025). "MPMs are more common in individuals with CDKN2A or CDK4 variants and typically present at a younger age compared to sporadic melanomas." (PMID 39941357, 2025). "This is clearly inaccurate: CDKN2A and CDK4 (MIM: 123829) PTVs are associated with malignant melanoma, and VHL (MIM: 608537) is associated with kidney cancer." (PMID 40073867, 2025). "It has been shown that melanoma tumors with loss of CDKN2A are often highly sensitive to CDK4/6 inhibition." (PMID 40904502, 2025). "Cyclin-dependent kinase inhibitor 2A [CDKN2A] gene and cyclin-dependent kinase 4 (CDK4) gene germline mutations, among other less commonly known mutations, are frequently identified genetic abnormalities in familial melanomas." (PMID 41463545, 2025). "The occurrence of MPMs and their anatomical distribution among heritable Rb survivors mirrors patterns observed in melanoma-prone families carrying CDKN2A or CDK4 mutations, further supporting potential shared genetic susceptibilities." (PMID 41234990, 2025). "Germline mutations in CDKN2A and CDK4 can significantly elevate an individual’s lifetime risk of developing melanoma." (PMID 39200315, 2024). "Disabling CDKN2A enhances the susceptibility to CDK4/6 inhibitors in certain types of cancer cells, such as melanoma." (PMID 38534309, 2024). "The main hereditary factors contributing to melanoma development are mutations in the CDKN2A or CDK4 gene, polymorphism of MC1R, and many nevi." (PMID 39340537, 2024). "Clinical study also shows that CDKN2A methylation, mutation, or loss of p16 (INK) protein are associated with increased melanoma susceptibility to CDK4/6 inhibitor Palbociclib." (PMID 38822443, 2024). "CDKN2A mutations are the most frequent in melanoma-prone families (20–40%) and affect the regulation of cell cycle by inhibition of CDK4." (PMID 38730639, 2024). "The frequent occurrence of oncogenic Gnaq Q209 mutations in Hgf-Cdk4 melanomas suggested a mechanistic connection between mutated Gnaq and Hgf-Met signaling." (PMID 38360887, 2024). "In melanoma, multiple mutations can affect CDK4/6 activity and increase proliferation by promoting the G1-S transition." (PMID 38732242, 2024). "In our work, we uncover transactivation of Met via oncogenic Gnaq/11, explaining the frequent occurrence and selection of Gnaq/11 mutations in primary melanomas of Hgf-Cdk4 mice." (PMID 38360887, 2024). "In the case of familial melanoma, germline mutations in certain high-risk genes, such as CDKN2A and CDK4, significantly increase the likelihood of developing melanoma, often at a younger age and with a higher propensity for multiple primary melanomas." (PMID 39518584, 2024).